APP (amyloid beta precursor protein)
Diseases named in the same sentence as APP in open-access papers (continued):
Sharing a sentence is not in itself a finding about the gene and the disease.
osteoporosis (10 papers, 2014 to 2025). A condition of reduced bone mass, with decreased cortical thickness and a decrease in the number and size of the trabeculae of cancellous bone (but normal chemical composition), resulting in increased fracture incidence. "When certain mutations in APP occur, osteoblast differentiation is suppressed, preventing new bone growth and laying the foundation for osteoporosis." (PMID 38236512, 2024). "The abnormal APP/Aβ deposition in osteoporotic bone seems to be associated with potent enhancement of osteoclast differentiation and activation, suggesting an important role for Aβ in the pathogenesis of osteoporosis." (PMID 29603567, 2018). "The diseases both involve some of the same signaling pathways, and some of the characteristic molecular hallmarks of AD, such as Aβ and APP, have been shown to play a role in osteoporosis as well." (PMID 38236512, 2024). "This study suggests that APP/Aβ and RAGE act as a common causative agent for AD and osteoporosis." (PMID 36117918, 2022). "A study in experimental AD-like mouse model (APP/PS1) found Aβ to be expressed in bones and potentially involved in the pathogenesis of osteoporosis in this mouse model of AD." (PMID 38285083, 2024).
behavioral disorders (9 papers, 2021 to 2024). "In order to verify the effects of the four compounds on behavioral disorders in APP/PS1 mice, we focused on species-specific nesting activities, because it is multi-brain-dependent spontaneous, which has been considered similar to ADL skills." (PMID 34638752, 2021). "APP/PS1 transgenic mice may have increased the behavioral disorder by activating aspartyl-trna synthetase, while Qi-Fu-Yin can improve this impairment." (PMID 36710967, 2022). "APP/PS1 transgenic mice may have increased the behavioral disorder by activating aspartyl-trna synthetase APP/PS1 transgenic mice may have increased the behavioral disorder by activating aspartyl-trna synthetase, while Qi-Fu-Yin can improve this impairment." (PMID 36710967, 2022). "In order to verify the effects of the four compounds on behavioral disorders in APP/PS1 mice, we focused on species-specific nesting activities, because it is multi-brain-dependent spontaneous, which has been considered similar to activities of daily living (ADL) skills." (PMID 34638752, 2021). "It is worth noting that, although most studies have shown that Aβ deposition is related to animal behavioral performance, some studies have shown that there is no good correlation between Aβ deposition in the brain and behavioral disorders in transgenic mice expressing APP mutations." (PMID 34685633, 2021). "The use of the PPAR-γ agonist levistolide A in APP/PS1 Tg mice (AD model) led to a decrease in the number of amyloid plaques and a decrease in inflammation and the severity of behavioral disorders." (PMID 35457077, 2022).
colorectal cancer (9 papers, 2012 to 2025). A primary or metastatic malignant neoplasm that affects the colon or rectum. "We utilized a human APP mutant knock-in AD mouse model to investigate how familial mutations influence colorectal cancer development." (PMID 41279101, 2025). "The amyloid precursor protein (APP) is upregulated in colorectal cancer and is linked to increased tumor cell proliferation, migration, and invasion." (PMID 41031085, 2025). "In addition, an increased APP response was observed to be associated with reduced survival rate, independently from stage of malignant disease, including lung, pancreatic, renal, and colorectal cancer and lymphoma." (PMID 26482227, 2015). "Clinical data indicate a distinct correlation between APP expression levels and survival in colorectal cancer patients." (PMID 41279101, 2025). "Clinical data further suggest differential roles of APP in the outcomes of human colorectal cancer patients." (PMID 41279101, 2025). "APP is also overexpressed in the papillary thyroid carcinoma and colorectal carcinoma." (PMID 31998645, 2019). "While an increased expression of APP is clearly established in AD, APP is also overexpressed in numerous cancers, including colorectal cancer." (PMID 23060898, 2012). "Moreover, extending this research to other malignancies, such as bladder, lung, pancreatic, and colorectal cancers, will be essential to establish whether APP processing represents a broader mechanism in cancer biology and to identify new opportunities for therapeutic intervention." (PMID 41614805, 2025). "Other AS events in various genes, such as VEGFA, APP, and NUMB, have been reported to regulate the development of colorectal cancer and have demonstrated potential as new targets for the diagnosis, prognosis, and treatment of this type of malignancy." (PMID 31443718, 2019).
hippocampal atrophy (9 papers, 2012 to 2024). "Amyloid beta (Aβ) deposition has been implicated in decreased glucose transporter-1 levels and hippocampal atrophy in brains of aged APP/PS1 mice at the capillary level without decreased capillary density." (PMID 22783187, 2012). "Brain imaging has revealed that APP mutations may result in a higher degree of hippocampal atrophy." (PMID 36142879, 2022). "A follow-up study in TASTPM mice compared to triple transgenic mouse model (APP/PS2/Tau) found that hippocampal atrophy was age-dependent, whereas in TASTPM mice, it was already detectable at the first investigated time point (<6 months of age)." (PMID 35203515, 2022).
experimental autoimmune encephalomyelitis (8 papers, 2011 to 2025). An autoimmune demyelinating disease of the central nervous system that is produced experimentally in animals by the injection of homogenized brain or spinal cord in Freund's adjuvant. "Genes highly expressed in adult homeostasis microglia and proinflammation-related genes significantly affected in experimental autoimmune encephalomyelitis, APP/PS1, and SOD1-mutant mouse brains were selected for analysis." (PMID 36720919, 2023). "At least some of the labelling (SMI31/32) observed here resembles that seen in experimental autoimmune encephalomyelitis and the observed APP labelling resembles neuritic beading induced by hypoxia/excitotoxicity in cultured neurons." (PMID 25727649, 2015). "We induced the experimental autoimmune encephalomyelitis (EAE) model of MS in two types of AD mouse models, Tg6799 and APP/PS1 mice." (PMID 35326455, 2022). "More intriguingly, injection of Aβ peptide into experimental autoimmune encephalomyelitis (EAE) delays disease onset; conversely, EAE gets worse following genetic deletion of the amyloid precursor protein (APP)." (PMID 31993048, 2019).
Hepatic steatosis (8 papers, 2017 to 2026). Steatosis is a term used to denote lipid accumulation within hepatocytes. "To assess the impact of hepatic steatosis on APP-processing gene expression, we divided the mRNA expression of liver samples from MASLD patients according to their histological steatosis grade, thereby excluding samples with fibrosis." (PMID 39201455, 2024). "Improvement in fasting blood glucose levels, blood lipid levels, hepatic steatosis, and scapular brown fat whitening;Reduction of Aβ 40–42 levels in the cerebral cortex of APP/PS1 mice and improved cognitive functions." (PMID 37111034, 2023). "In addition, mice with hepatic steatosis show an increased accumulation of APP in the liver that decreases the scavenging action of the liver towards Aβ, potentially enhancing Aβ accumulation in the periphery, including the brain, thus promoting AD." (PMID 41515287, 2026). "After treatment with Akk, the APP/PS1 mice showed obviously reduced blood lipid levels, improved hepatic steatosis and scapular brown fat whitening." (PMID 32321934, 2020). "Interestingly, lipid metabolism disorders in APP/PS1 mice treated with Akk were significantly improved, showing a decrease in serum Chol and TG levels, and hepatic fat scores showed ameliorative hepatic steatosis (p < 0.05, respectively)." (PMID 32321934, 2020). "The fact that a high-fat diet (HFD) for 14 weeks leads to the development of fatty liver with no signs of fibrosis in mice led us to use this model to explore the impact of hepatic steatosis on the expression of APP, APP degradation, and Aβ-42-producing proteins in the liver." (PMID 39201455, 2024). "We found that APP/PS1 mice showed significantly increased food intake, and the emergence of lipid metabolism disorders, such as increased levels of total cholesterol and triglycerides, liver steatosis, scapular brown adipocytes whitening, which were aggravated when treated with HFD." (PMID 32321934, 2020).
hyperhomocysteinemia (8 papers, 2011 to 2025). A serious metabolic condition caused by mutations in the MTHFR gene, medications, or nutritional deficiency. "In fact, new studies show that the inhibition of protein phosphatase 2A methyltransferase (PPMT) caused by hyperhomocysteinemia promotes tau and leads to APP deregulation." (PMID 26590557, 2015). "Hyperhomocysteinemia is an established risk factor for AD and is experimentally associated with the development of hallmark pathological features of AD, including tau and APP phosphorylation, and amyloidogenesis." (PMID 33380425, 2021). "In addition, hyperhomocysteinemia increases Aβ production in rats, probably through enhanced expression of γ-secretase and APP phosphorylation, placing hyperhomocysteinemia upstream of increased Aβ production." (PMID 25249976, 2014). "Liraglutide reduces APP expression and phosphorylation, BACE1 and PSEN1, and increases α-secretase in hyperhomocysteinemia and AlCl3-induced AD." (PMID 41146261, 2025). "A previous study reported that EGB761, a herbal extract from Ginkgo biloba, has good effects against various cognition deficits in elderly db/db (-/-) diabetic mouse, APP/PS1 mouse, and rats with hyperhomocysteinemia." (PMID 33539323, 2021).
hyperlipidemia (8 papers, 2020 to 2025). "Importantly, A2M, APP, CLU, IGF2 and PLAU are not among the hyperlipidemia associated genes, they are retrieved only after obtaining the disease module with DIAMOND." (PMID 34824199, 2021).
Intellectual disability (8 papers, 2014 to 2023). "Our findings suggest that APP may therefore represent a new therapeutic target and/or biomarker for FXS and for other neurodevelopmental disorders and intellectual disabilities, such as ASD, that share with FXS the dysregulation of APP processing." (PMID 36899894, 2023). "Furthermore, DYRK1A phosphorylates several neurodegenerative diseases associated proteins, such as APP and α-synuclein, and has been associated with intellectual disability and targeted to improve cognitive performance in subjects with DS (without AD) and other intellectual disabilities." (PMID 35630721, 2022). "Familial cases of AD with microduplication of the APP gene have peculiar pathology with prominent amyloid angiopathy but do not show intellectual disabilities while individuals with DS rarely show vascular and mixed dementia but intellectual disabilities are prevalent." (PMID 27378871, 2016).
Neurodegeneration (8 papers, 2013 to 2024). Progressive loss of neural cells and tissue. "APP is an integral membrane protein that is concentrated at the synapse, not only in the CNS but also in the NMJ, implicating APP as a shared molecule that underlies the development of neurodegeneration diseases and sarcopenia." (PMID 37175515, 2023). "We have exploited XPCT to study the APP/PS1dE9 mouse model of AD, a progressive neurodegenerative disorder associated with aberrant production of Aβ depositing in the brain as extracellular plaques, especially in the cortical and the hippocampal areas." (PMID 33240038, 2020). "Other than the potential candidate genes, the compact SPNW also included many significant connecting proteins like APP, BACE1, CCNA2, CREB1, E2F1, EGR1 and MDM2 which were previously implicated to play critical roles in many neurodegeneration disease pathogenesis including Alzheimer’s." (PMID 26784894, 2016). "The compact shortest path network included many noteworthy connecting proteins like APP, CREB1, HSP90AA1, MAPT and PTEN which were previously implicated to play critical roles in many neurodegeneration disease pathogenesis and couple of them were indicated to have neuroprotective mechanism." (PMID 24688734, 2013).
synucleinopathy (8 papers, 2017 to 2025). A neurodegenerative disease that is characterized by the abnormal accumulation of aggregates of alpha-synuclein protein in neurons, nerve fibers or glial cells. "The overall aims of this work were to characterise amyloidogenic processing of APP in cell models of synucleinopathy, and to find evidence of the underlying cell mechanism." (PMID 28187176, 2017). "The presence of APP in the list of revealed upstream regulators indicates that protein aggregation occurs during synucleinopathy." (PMID 36523604, 2022). "As with APP/PS1 mice, CatB-enhancing PADK treatment in animals with early α-synucleinopathy led to an evident link between pathogenic protein reduction and improved synaptic marker levels." (PMID 31505809, 2019). "Successful characterisation of APP processing was achieved in multiple synucleinopathy cell models, confirming the potential importance of α-synuclein to β-amyloid production, however the underlying cell mechanism is tentative." (PMID 28187176, 2017). "Previous studies of APP/PS1/Tau/α-syn transgenic mice demonstrated advanced synucleinopathy." (PMID 40707862, 2025). "Altogether, APP, CLU, CALCA, and SOD1 may contribute to the α-synuclein-associated synucleinopathy, whereas NEDD4 by posttranslational modification protects against the formation of toxic α-synuclein inclusions." (PMID 36523604, 2022). "In contrast to our synucleinopathy models, the amyloid precursor protein (APP) knock-in mice modeling AD used in this study only showed rare Aβ inclusions that could only be detected in quite old mice." (PMID 33743820, 2021). "In summary, β-secretase-mediated processing of APP may be potentiated by high levels of α-synuclein, and could represent a contributing mechanism of β-amyloid accumulation in synucleinopathy disease." (PMID 28187176, 2017). "The appearance of APP, a series of inflammatory mediators, and MAPK kinases as the upstream regulators indicate that the upstream SNCA regulators contribute to synucleinopathy." (PMID 36523604, 2022).
age (7 papers, 2014 to 2025). A temporal measurement of the time period elapsed since an identifiable point in the life cycle of an organism. "Amyloid precursor protein (APP) causes Aβ, which is a major component of age plaques, whereas the PS1 and PS2 A components of gamma-secretase cleavage APP produce Aβ." (PMID 37259422, 2023).
autism spectrum disorder (7 papers, 2016 to 2025). A spectrum of developmental disorders that includes autism, and Asperger syndrome. "Metabolites of the Amyloid-β precursor protein (APP) proteolysis may underlie brain overgrowth in Autism Spectrum Disorder (ASD)." (PMID 37799731, 2023). "Hsa-mir-328 has been reported to be associated with a variety of neurologic disorders, such as autism spectrum disorder, Huntington’s, Parkinson’s, and Alzheimer’s, and the biological functions of its targeting genes APP and BACE1 were validated experimentally in mouse brain tissues." (PMID 32154224, 2020). "Ethiopathogenesis of autism spectrum disorder (ASD) involves an array of genetic, epigenetic and environmental factors and is associated with dysregulation of some basic cellular homeostatic mechanisms, including processing of APP." (PMID 37305553, 2023).
hemorrhagic stroke (7 papers, 2009 to 2022). A stroke caused by a bleed on the brain. "APP upregulation, relevant for AD, is a key element also in general brain iron homeostasis since it actively proceeds during vascular accidents protecting in turn neurons from heme release in ischemic/haemorrhagic stroke, ascribing it a great value also for VaD patients." (PMID 29518107, 2018). "As a matter of fact, substitutions at APP 693 codon that cause either a loss of charge (E22Q; Dutch APP) or a change of charge (E22K; Italian APP) show increased binding to and degeneration of cerebrovascular smooth muscle cells and, not surprisingly, both of them lead to CAA/haemorrhagic strokes." (PMID 19468344, 2009). "The Arctic and Iowa APP carriers resemble the Flemish APP carriers by having a mixed AD/severe CAA phenotype, although haemorrhagic strokes are not observed." (PMID 19468344, 2009).
insomnia (7 papers, 2021 to 2025). A sleep disorder characterized by difficulty in falling asleep and/or remaining asleep. "Based on these results, we hypothesize that TGFBI may contribute to insomnia in conjunction with the regulation of APP and miRNAs, among other factors." (PMID 38725646, 2024). "It is uncertain whether activation of VTAVgat neurons can slow insomnia in APP/PS1 mice." (PMID 37032820, 2023). "In the results, HP, FGA, FGG, FGB, and MMP9 were upregulated in patients with insomnia, and FN1, APP, EGF, AHSG, and IGF1 were downregulated compared with controls." (PMID 35958162, 2022). "Among them, HP, MMP9, FGA, FGB, and FGG were validated as upregulated, and APP, AHSG, and IGF1 were downregulated in patients with insomnia." (PMID 35958162, 2022). "Among them, the expression of F2, HP, FGA, FGB, FGG, and ApoB were upregulated in insomnia patients with wakefulness, and A2M, AHSG, APP, and ApoA1 were downregulated." (PMID 33511209, 2021). "Possible links between insomnia, OSA, and AD pathophysiology in adults with DS must be tested in future studies and with larger samples to address these possibilities, especially given the mechanistic role of APP triplication on amyloid-β overproduction and AD in adults with DS." (PMID 38875029, 2024).
retinal degeneration (7 papers, 2012 to 2023). Degeneration of the retina. "Using TUNEL to look at NMDA-induced apoptosis in APP and PS1 single transgenic mice and APP/PS1 double transgenic mice has yielded potential insight into how Aβ may cause retinal degeneration." (PMID 22666623, 2012). "APP also induces erroneous CCR, and knockdown of polo, another key regulator of the cell cycle, partially rescues APP-induced locomotor dysfunction and retinal degeneration and prevents a shortened lifespan by repressing APP-induced CCR." (PMID 32019113, 2020). "Overexpression of GULP1 also reduced APP/BACE-mediated retinal degeneration, rescued motor dysfunction and extended longevity of the flies." (PMID 29245900, 2017). "Although knocking-down polo alone had no distinguishable effect on eye development, it partially suppressed APP-induced retina degeneration, suggesting Polo is indispensable for APP-induced retina toxicity in adult eyes." (PMID 26597721, 2015). "Importantly, we also report retinal degeneration in APP/PS1 mice, including Aβ deposits and reduced choline acetyltransferase levels, loss of melanopsin retinal ganglion cells and functional integrity mainly of inner retina layers." (PMID 37004084, 2023). "Finally, we showed that eye-specific expression of APP induced retina degeneration and cell cycle re-entry, both phenotypes were mildly ameliorated by loss of Polo." (PMID 26597721, 2015). "Several of these have been reported to maintain retinal functions including APP which is expressed in neuronal cells of the inner retina and involved in inner retinal circuitry 46, and APLP2 whose deletion induced retinal synaptopathy and retinal degeneration." (PMID 36185601, 2022). "Amyloid-beta (Aβ) peptides are present in drusen and its precursor, amyloid precursor protein (APP), is expressed by the RPE and retinal ganglion cells, but their roles in retinal degeneration remain unclear." (PMID 34210002, 2021).